SP1 (Sp1 transcription factor)
Diseases named in the same sentence as SP1 in open-access papers (continued):
Sharing a sentence is not in itself a finding about the gene and the disease.
gastric cancer (continued). "Since above evidence showed that Sp1 participated in the transcriptional regulation of MMP-14 in gastric cancer, we proposed that Sp1 might play an important role in sub-cytotoxic MJ-induced decrease in the migration, invasion and angiogenesis of gastric cancer cells." (PMID 23394613, 2013). "Nevertheless, the role of SP1 in gastric carcinoma has not been clarified, although a line of evidence clearly emphasizes its clinical importance; SP1 overexpression is reportedly correlated with angiogenic potential and poor prognosis in human gastric carcinoma." (PMID 23437057, 2013). "Furthermore, co-overexpression of RAGE, Sp1, and MMP2 and accumulation of AGEs in cancer tissues were found in invasive cancer tissues, which suggested that the accumulation of glucose-derived AGEs may contribute to gastric cancer progression by regulating the expression of RAGE, Sp1, and MMP2." (PMID 29262634, 2017). "Other investigators have suggested that Sp1, rather than AP-1, plays a critical role in regulating VEGF-A expression in gastric cancer cells as well as in supporting the constitutive expression of VEGF in human pancreatic cancer." (PMID 27637085, 2016). "Western blot and real-time quantitative RT-PCR indicated that the expression of Sp1, MMP-14, and VEGF was significantly higher in gastric cancer tissues than that of adjacent non-neoplastic tissues." (PMID 23394613, 2013). "Gastric cancer patients whose tumors highly expressed ZEB2 or Sp1 had a lower overall survival than those whose tumors did not (n = 631, P = 0.00053 and P = 0.000024 for ZEB2 and Sp1, respectively) when survival within previously published data sets was analyzed using kmPlotter." (PMID 29416649, 2018).
lung cancer (115 papers, 2012 to 2026). A malignant neoplasm involving the lung. "We then sought to elucidate the molecular mechanism underlying the decreased level of Sp1 in E2-A549 and A549-T24 lung cancer cells." (PMID 35034634, 2022). "Taken together, our results strongly suggest the essential role of Sp1 in maintaining the basic constitutive expression of PDSS2, and the pathogenic implication of Sp1-mediated PDSS2 transcriptional repression in lung cancer cells." (PMID 31783675, 2019). "In investigating the clinical relevance of Nm23-H1/Sp1 levels, we found a positive correlation between lung cancer patients with poor prognosis and low levels of Sp1 and Nm23-H1, suggesting an association between Nm23-H1/Sp1 levels and survival rate." (PMID 28831131, 2017). "The main purpose of the study aims to evaluate diagnostic utility and correlation among E6, LKB1, SP1, and hTERT as tumor markers in brushing cells of patients with lung cancer." (PMID 28813465, 2017). "The results indicated again the association between CBP and transactivators Sp1 and AP-2 in lung cancer cells." (PMID 25294805, 2014). "Multiple human cancer types have been found to be associated with the expression of Sp1 and MMPs, including glioma cells, lung cancer cells, and ovarian cancer." (PMID 23892595, 2013). "For instance, in lung cancer, Sp1 acetylation is implicated in tumor macrophage polarization." (PMID 39228402, 2024). "However, Sp1 downregulation in the late stages of lung cancer leads to a decrease in miR-182 expression, causing FOXO3-mediated tumor metastasis by increasing the expression of N-cadherin, ADAM9, CDH9, and CD44." (PMID 37438760, 2023). "As a consequence, we supposed that the hypermethylation of the P1 KEAP1 promoter might lead to the loss of SP-1 and AP-2 binding via inhibiting its expression at the first two, 4th and 5th CpG sites in the analyzed lung cancer cells, respectively." (PMID 31159323, 2019). "Sp1-mediated PDSS2 transactivation is implicated in the pathogenesis of lung cancer." (PMID 31783675, 2019). "Since the Sp1 level is tightly regulated during lung cancer progression, understanding the molecular mechanisms underlying the regulation by Nm23-H1/hnRNPA2B1 of Sp1 expression in the various stages of lung cancer will be beneficial for lung cancer therapy in the future." (PMID 28831131, 2017). "However, we used the transfection and interference technology to regulate the E6 in lung cancer cells, the results showed that the expression of SP1 protein was associated with the change of E6." (PMID 28813465, 2017). "Previous reports indicated that in hepatocellular carcinoma, esophageal carcinoma, lung cancer, and prostate cancer, the expression level of Sp1 was also correlated with the expression level of c-Met." (PMID 40125551, 2025). "For instance, atractyloide-1 has been shown to impede the growth of lung cancer cells by activating ERK1/2-mediated Sp1 phosphorylation." (PMID 39228402, 2024). "The relationship between HDAC2, HDAC10, and Sp1 acetylation in lung cancer progression is characterized by an upstream and downstream dynamic." (PMID 39228402, 2024). "Specificity protein 1 (Sp1)-mediated overexpression of miR-182 has been also reported to contribute to lung cancer progression." (PMID 37438760, 2023). "For example, Sp1 induces expression of multiple miRNAs in lung cancer cells (miRNA-3194-5p, miRNA-218-5p, miRNA-193-5p, miRNA-182-5p and miRNA-135-5p), miRNA-200 in breast cancer cells, and miRNA-365 in Hela cells." (PMID 36982239, 2023). "The effect of AuNPs loaded with small interfering RNAs (siRNAs)-SP1 on the radiosensitizing effect and mechanism of AuNPs-si-SP1 on lung cancer has been studied." (PMID 37510275, 2023). "SP1 can be combined with long noncoding RNA (lncRNA) promoters to promote the proliferation, migration, and invasion of lung cancer cells by regulating lncRNA expression." (PMID 35313857, 2022).
lung cancer (continued). "For example, in lung cancer, higher SP1 expression with lower PDSS2 expression was found significantly correlated with poor prognosis." (PMID 36467048, 2022). "E2 increases RNF4 expression to repress Sp1 levels in premenopausal women with lung cancer, thus decreasing the expression of several miRNAs that can target CD44 and ultimately leading to cancer malignancy." (PMID 35034634, 2022). "In summary, Sp1 negatively regulates lung cancer migration and stemness abilities in women with lung cancer, thus increasing Taxol-induced cytotoxicity." (PMID 35034634, 2022). "Our previous studies have indicated that Sp1-mediated miR-182 expression silences FOXO3 to enhance lung cancer malignancy." (PMID 35034634, 2022). "Here we demonstrate that circ-0001875, identified as a novel circRNA upregulated in lung cancer, regulates the miR-31-5p/SP1 axis with an oncogenic role to promote EMT via a TGFβ/Smad2 signal pathway." (PMID 35473752, 2022). "Sp1 level accumulated strongly in early stage and then declined in late stage, which is important for lung cancer cell proliferation and metastasis during tumorigenesis." (PMID 38091511, 2022). "There was a similar study reported in lung cancer that demonstrated that miR‐326/Sp1/KLF3 regulatory axis is involved in the development of lung cancer." (PMID 35715760, 2022). "Eight lung cancer specimens collected from lung cancer patients were used to study the protein levels of Sp1 and CD44." (PMID 35034634, 2022). "Studies in lung cancer cohorts have indicated that Sp1 is upregulated in most patients with early-stage lung cancer and promotes cancer growth." (PMID 35034634, 2022). "In this study, we investigated the relationship among the Sp1 level, sex and survival rate of 331 lung cancer cohorts, including 185 male and 146 female cohorts by Kaplan–Meier survival curves and hazard ratio (HR)." (PMID 35034634, 2022). "In mouse models of lung cancer, low SP1 expression can effectively inhibit tumour growth and nicotine-induced lung cancer cell growth." (PMID 36699463, 2022). "Our previous studies have indicated that the Sp1 levels are decreased in late-stage lung cancer and related to a poor prognosis." (PMID 35034634, 2022). "Sp1 levels accumulate strongly in the early stage and then decline in the late stage, which is important for lung cancer cell proliferation and metastasis during tumorigenesis." (PMID 38091511, 2022). "In this study, we found that AP2, ATF3, c-Myc, NF-YA, and SP1 are critical to USP22 mRNA expression in lung cancer cells." (PMID 36123698, 2022). "The data indicated that E2 treatment increased the tumor area in the lung, but GFP-Sp1 overexpression reversed this effect, suggesting that Sp1 negatively regulates lung cancer metastasis." (PMID 35034634, 2022). "The ubiquitination signal of Sp1 was increased in E2-A549 and A549-T24 lung cancer cells, but the mRNA level was unchanged in A549-T24 cells." (PMID 35034634, 2022). "In this study, we found that the increase in Sp1 degradation in premenopausal women with lung cancer can inhibit Sp1-mediated miRNA expression, thus activating EMT-related gene expression and leading to lung cancer malignancy." (PMID 35034634, 2022). "Herein we found that there was an inverse correlation between the Sp1 level and poor prognosis in the late-stage premenopausal female lung cancer patients." (PMID 35034634, 2022). "Our previous studies have indicated that Sp1 levels are increased in the early stage of lung cancer progression but decrease during the late stage, leading to poor prognosis." (PMID 35034634, 2022). "Although Sp1 positively regulates cancer proliferation, our previous studies indicate that Sp1 negatively regulates lung cancer metastasis in the late stage." (PMID 35034634, 2022). "The clinical relevance between Sp1 levels and survival rates in young women with lung cancer was studied by immunohistochemistry." (PMID 35034634, 2022).
lung cancer (continued). "Higher SP1 expression and lower PDSS2 expression have been found to be significantly associated with poor prognosis in lung cancer patients." (PMID 35313857, 2022). "Several reports have also shown that Sp1 and ER can coregulate gene expression, implying that Sp1 and estrogen receptors coregulate lung cancer progression in women." (PMID 35034634, 2022). "To investigate the role of Sp1 in E2-mediated lung cancer progression, we first studied the roles of E2 and Sp1 in lung cancer progression and drug resistance in vitro." (PMID 35034634, 2022). "After review of the literature of the candidate genes, we found that SP1 was regulated by miR-31-5p to promote cancer proliferation, migration, and invasion and is also involved in lung cancer proliferation and metastasis processes." (PMID 35473752, 2022). "In this study, we found that Sp1 expression was decreased in premenopausal women with late-stage lung cancer, resulting in a poor prognosis." (PMID 35034634, 2022). "In lung cancer, SP1 participates in the induction of matrix metalloproteinase-2 (MMP-2) and matrix metalloproteinase-9 (MMP-9) to accelerate cell invasion." (PMID 34257529, 2021). "CCR7 combined with the ligand can promote the metastasis of lung cancer cells by up-regulating the expression of sp1." (PMID 33158173, 2020). "We also found that suppression of SP1 contributed to the inhibition of human lung cancer cell growth (Chen, Tang, Wu, Zheng, Yang & Hann, 2015)." (PMID 31823440, 2020). "Firstly, we detected the expression of Sp1 in lung cancer tissues through real‐time PCR and Western blot." (PMID 30485570, 2019). "As expected, the mRNA and protein levels of Sp1 were also elevated in different lung cancer cell lines compared with that in the HBECs." (PMID 30485570, 2019). "The results showed that Sp1 was upregulated in lung cancer tissues compared with that in the adjacent normal tissues (P < 0.001), which correlated with the expression of KLF3 in lung cancer tissues." (PMID 30485570, 2019). "In summary, our study provides evidence that miR‐326/Sp1/KLF3 regulatory axis involves in lung cancer cell proliferation, migration and invasion, which provide leads for the further therapy to patients with lung cancer." (PMID 30485570, 2019). "The results show that the expression of Sp1 is negatively correlated to that of PDSS2 in lung cancer tissues." (PMID 31783675, 2019). "Our data demonstrate that miR‐326/Sp1/KLF3 regulatory axis is involved in the development of lung cancer, which hints the potential target for the further therapeutic strategy against lung cancer." (PMID 30485570, 2019). "The IHC data also indicated that the level of Sp1 in lung cancer tissues was evidently elevated compared to that in normal lung tissues." (PMID 30485570, 2019). "Previously, it was reported that NZ28—an inhibitor of several transcription factors including HSF-1, SP1, and NF-kB—can increase the radiosensitivity in human lung cancer cells." (PMID 31569342, 2019). "Of note, the expression of Sp1 and PDSS2 are negatively correlated, and higher Sp1 expression with low PDSS2 expression is significantly associated with poor prognosis in lung cancer." (PMID 31783675, 2019). "It has been unveiled that nicotine induces binding of Sp1 on α7-nAChR promoter, leading to transcriptional activation of α7-nAChR in lung cancer, which in turn facilitates tumor growth and progression." (PMID 29728663, 2018). "More importantly, our in vivo data were consistent with the findings from that in vitro, confirming the enhanced effect of BBR in the presence of MET on inhibition of lung cancer 8, 60, 61, and regulation of SP1, PDPK1 and DNMT1 expressions." (PMID 28840963, 2018). "Recently, we found overexpression of SP1 mRNA in the bronchial brushing cells of patients with lung cancer." (PMID 28813465, 2017).
lung cancer (continued). "In this paper, E6, LKB1, SP1, and hTERT mRNA expression levels were detected in brushing cells of patients with lung cancer (n = 106) and with benign lung disease (n = 68) by qRT-PCR." (PMID 28813465, 2017). "In order to investigate the roles of LKB1 on regulating the expression of SP1 and hTERT in lung cancer cells, we transiently transfected pcDNA3-LKB1-His into the low expression NSCLC cell lines, A549 cells." (PMID 28813465, 2017). "We had demonstrated for the first time that E6 upregulation of hTERT by downregulated LKB1 and upregulated SP1 in lung cancer cells." (PMID 28813465, 2017). "The data indicated that lung cancer patients with higher levels of Sp1 and Nm23-H1 also exhibited high levels of hnRNPA2/B1, suggesting a positive correlation between the levels of Sp1, Nm23-H1 and hnRNPA2/B1 during lung cancer formation." (PMID 28831131, 2017). "Previous studies showed similar results on TIMP‐3 regulation which is induced by ERK phosphorylation and the downstream transcriptional factor, Sp1 in human lung cancer cells." (PMID 28672103, 2017). "In conclusion we demonstrated that the expression of E6, SP1, and hTERT mRNAs were increased in brushing cells of patients with lung cancer compared with benign disease by qRT-PCR (P < 0.01)." (PMID 28813465, 2017). "In this study, we found that Nm23-H1 is increased in the early stages but is decreased in the late stages of lung cancer progression, which is correlated with the Sp1 level." (PMID 28831131, 2017). "In the present study, the expression of E6, SP1 and hTERT mRNAs were increased in the lung cancer group than in the benign group by qRT-PCR (P < 0.01), conversely, LKB1 mRNA was decreased in the lung cancer (P < 0.01)." (PMID 28813465, 2017). "In conclusion, in this study, we provided evidence to support a role for the Nm23-H1/hnRNPA2/B1/Sp1 axis in the regulation of lung cancer progression; these findings will contribute to a better understanding of lung cancer progression." (PMID 28831131, 2017). "The results suggest that CUG2 and TGF-β synergistically induce the EMT by cooperation of Sp1 and Smad2/3, leading to metastasis of lung cancer cells." (PMID 27974707, 2017). "Next, the relationship between Sp1/Nm23-H1 expression and the prognosis of patients with lung cancer was addressed." (PMID 28831131, 2017). "Of 111 patients with stages I and II lung cancer, 105 (94.6%) exhibited high Sp1 expression, whereas only six (5.4%) had low Sp1 expression." (PMID 28831131, 2017). "Our recent studies have indicated that specificity protein-1 (Sp1) accumulates substantially in the early stage of lung cancer but is partially decreased in the late stages, which is an important factor in the progression of the cancer." (PMID 28831131, 2017). "Long-term persistent infection of high-risk HPV16 E6 caused LKB1 loss, and E6 upregulated the expression of both protein and mRNA of hTERT in lung cancer cells mediated by SP1." (PMID 28813465, 2017). "Comparison of the expression levels of Sp1 and Nm23-H1 in the different stags demonstrated that Sp1 and Nm23-H1 were highly expressed in most of the patients with stage I and II lung cancer (98%)." (PMID 28831131, 2017). "Meanwhile, we noted that the level of Sp1 was higher in the high-metastatic lung cancer cell line 95D." (PMID 27829234, 2016). "For example, in lung cancer cells, overexpression of SP1 can upregulate the expression of ABCG2, which is one of the ATP binding cassette (ABC) transmembrane proteins that influence the chemotherapeutic resistance of cancer cells." (PMID 26922862, 2016). "The transcriptional factors Sp1 was reported to be the target of miR-29c in kidney tubular epithelial cells and we found that the expression of Sp1 was enhanced in lung cancer cell lines 95C, 95D and A549 than that in normal human epithelial cell line BEAS-2B." (PMID 27829234, 2016).